DNMT3A (DNA methyltransferase 3 alpha)
Diseases named in the same sentence as DNMT3A in open-access papers (continued):
Sharing a sentence is not in itself a finding about the gene and the disease.
leukemia (continued). "We removed from analysis all samples that had an evidence of leukemia or lymphoma developed before the DNA collection as well as those samples that have mosaic missense mutations in DNMT3A to estimate the contribution of the PTVs only." (PMID 29263833, 2017). "To date, numerous functional experiments have provided a better understanding of the effects of DNMT3A mutation on leukemia pathogenesis." (PMID 28127428, 2017). "The observation that loss of a single allele is sufficient to shorten survival and elicit leukemia development highlights the importance of Dnmt3a stoichiometry in maintaining appropriate hematopoietic stem cell function." (PMID 27636998, 2016). "The data presented in this report demonstrate that conditional deletion of Dnmt3a and simultaneous “knock in” of Flt3ITD/+, cooperate to drive leukemia development at a faster rate than Dnmt3a loss alone." (PMID 27636998, 2016). "Mutated DNMT3A occurs in hematopoietic stem cells and is considered a driver mutation in initiating leukemia." (PMID 27724883, 2016). "MicroRNA-143 has been experimentally confirmed to represses DNMT3A expression in colon and breast cancer cell lines, and inhibit growth by causing apopotosis in leukaemia cells." (PMID 27814400, 2016). "Screening of leukemia-initiating mutations, such as DNMT3A, NPM1 or IDH1/2 mutations should be performed at diagnosis but only NPM1 and IDH1/2 are robust target for MRD monitoring." (PMID 26486081, 2015). "Our results indicated that most of patients(11/14) with DNMT3A mutation died of leukemia after 6 months treatment, two patient were alive due to allogeneic stem cell transplant and AML-M3 type." (PMID 23305405, 2013). "We sequenced all coding exon of DNMT3A using DNA from leukemia cells and identified 14 heterozygous mutations (13.9%)." (PMID 23305405, 2013). "The Dnmt3a enzyme is required for the establishment of normal methylation patterns, and mutations in Dnmt3a have been described in leukemias." (PMID 23284304, 2012). "Its homolog DNMT3A was recently found to be mutated in a subset of leukemia with a normal karyotype." (PMID 22253721, 2012). "In contrast, aggressive transplantation leukemia is observed in Flt3ITD/wt, Tet2+/−, and Dnmt3a+/− mice within the same time scale, mainly associated with quantitative rather than qualitative differences in gene expression relative to Tet2mut/ Flt3mut or Dnmt3amut/ Flt3mut mice." (PMID 39078434, 2025). "DNMT3A mutations facilitate leukemogenesis with other leukemia-related genes." (PMID 39078434, 2025). "Since WT1 or DNMT3A mutations are presented in only 20.5% patients with CEBPAbZIP-inf who had relapsed, it’s apparent that non-genetic drivers underpin a large proportion of functional variation in leukemia." (PMID 38253683, 2024). "Given that different types of diseases in the same DNMT3A KO model display distinct lineage-specific methylation profiles, deficiency of DNMT3A may induce pre-leukemia, which then transform into different types of leukemia depending on additional hits." (PMID 36675240, 2023). "This temporal sequence is in line with previous observations that preleukemic DNMT3A mutations precede the acquisition of leukemia-driving mutations and may persist in remission after intensive chemotherapy." (PMID 37591941, 2023). "In addition, DNMT3A mutations, together with other mutations, were related to the prognosis of leukemia patients." (PMID 36797244, 2023).
leukemia (continued). "Therefore, TET2 dioxygenase inhibitors should be explored therapeutically to reverse PARPi resistance in DNMT3A-deficient leukemias." (PMID 36497275, 2022). "There are many different site-specific DNMT3A mutations in leukemia and CHIP, and therefore, it might be anticipated that targeting of specific exons is of functional relevance." (PMID 35705990, 2022). "The DNMT3A mutation can cause significant changes in epigenetic modifications and is one of the essential regulatory factors for the occurrence and development of leukemia." (PMID 34093541, 2021). "Furthermore, FLT3-ITD leukemias with mutations in NPM1 or DNMT3A exhibit a different drug response mechanism to the FLT3 inhibitor quizartinib, where the cell differentiation effect predominates over the cytotoxic mechanism." (PMID 33592069, 2021). "TET2/DNMT3A was co-mutated in human lung, breast, skin and kidney cancers and frequently in angioimmunoblastic and peripheral T cell lymphomas and several types of leukemia." (PMID 34039392, 2021). "The FLT3-mutation like pattern was enriched in NPM1 and DNMT3A mutant leukemias." (PMID 33592069, 2021). "Thus, Dnmt3a deficiency establish an epigenetic state somehow predisposing to the emergence of cooperating mutations leading to overt leukemia in mice." (PMID 33159179, 2021). "Using variant allele frequencies to infer the chronological sequence of these events in leukemia development, it was shown that mutations in DNMT3A likely develop first in hematopoietic stem cells (or other mutations causing CH), followed by NPM1c second in a CMP, and FLT3 mutations (or RAS) third." (PMID 32545659, 2020). "DNMT3A mutations occur in hematopoietic stem cells and lead to a clonal expansion of these cells, a process known as clonal hematopoiesis (CH), which is an age-related process that predisposes to leukemia." (PMID 32545659, 2020). "KRAS is the most common driver mutation in lung cancer, and is highly co-occurrent with KEAP1 and STK11 mutations, NOTCH1 has a putative role in skin cancer, loss of PTEN is the most common genomic alteration in glioblastoma, and DNMT3A has been associated with leukemia and myelodysplasia." (PMID 32374727, 2020). "Loss of DNMT3a has been reported to be associated with leukemia pathogenesis and poor prognosis." (PMID 32849814, 2020). "In the mechanism study, we revealed that DKI mice showed significantly altered gene expression patterns with involvement of Myc pathway activation, indicating a potential therapeutic target in DNMT3A mutation-related leukemia which needs to be further investigated." (PMID 31703632, 2019). "All of the three patients with increased DNMT3A mutation burden had leukemia transformation." (PMID 29619119, 2018). "Furthermore, highly recurrent somatic DNMT3A mutations have been identified in several types of leukemia and are associated with poor prognosis of the diseases, suggesting a causal link between loss of DNMT3A function and tumorigenesis." (PMID 27462454, 2016). "OCI-AML3, a leukemia cell line harboring the hotspot DNMT3A R882C mutation, could proliferate in NOD/SCID mice and induce paralysis and finally death." (PMID 27724883, 2016). "One possible interpretation of this finding is that DNMT3A mutations play a more important role in pre-LSC transcriptional changes in HSPC that allow for leukemia to develop in more differentiated blasts, and that these changes are in effect “averaged-out” with standard ensemble techniques." (PMID 27597933, 2016).
leukemia (continued). "Studies of such phenomena have defined a hierarchical structure among particular leukemia mutations, with some, such as those affecting the gene DNMT3A, displaying the characteristics of leukemia-initiating lesions and driving the expansion of hemopoietic cell clones prior to the onset of leukemia." (PMID 25732814, 2015). "Furthermore, DNMT3A mutations were associated with several clinical characteristics in leukemia." (PMID 36797244, 2023). "Although their association to AML development remains correlative, it is tempting to speculate that the early detection and direct inhibition of early mutations such as DNMT3A-R882H might lead to the leukemia prevention by knockdown or extinction of the mutated cell clones." (PMID 36457063, 2022). "Consequently, DNMT3A-deficient leukemia cells are resistant to PARPi." (PMID 36497275, 2022). "Importantly, one could find examples of hypomethylation driving leukemias (DNMT3A mutations) as well as of hypermethylation (IDH mutations) driving the leukemia." (PMID 34209564, 2021). "Also, due to the clinical interest in mutated epigenetic modifiers in leukemia, strategies used to target DNMT3A mutant hematological malignancies may be relevant to CCS35." (PMID 31624251, 2019). "Thus, although DNMT3A protein function must be almost completely lost in order to cause malignancy, heterozygous loss-of-function mutations are often found combined with a driver mutation in the development of frank leukemia." (PMID 29464054, 2018). "Similar mechanisms might be also functional among DNMT3A-mutated leukemias (right) where DNMT3A mutations perturb efficient CpG methylation at cis-regulatory sites leading to elevated histone acetylation and increased binding of DOT1L-associated complexes that harbor YEATS-containing AF9 and ENL." (PMID 29075615, 2017). "In the CTRL-ROY group, enrichment was significant for “leukemia” and “acute leukemia” terms (NES = 2.12, Q = 0.03), driven by key myeloid malignancy-associated genes DNMT3A, IDH1, SRSF2, and TET2." (PMID 41371958, 2026). "MLL rearrangements and mutations in DNMT3A and NPM1 were more frequently detected among the sensitive samples, consistent with previous findings that MLL-leukaemia are highly sensitive to LSD1i19." (PMID 40240608, 2025). "Small molecule inhibitors of DOT1L restored HOXA/B gene repression in vitro and proved effective in DNMT3A mutant leukemia." (PMID 39078434, 2025). "Spleen size and weight were increased in moribund miR196b–/–Dnmt3a+/–Flt3ITD as compared to age-matched Dnmt3a+/-Flt3ITD mice, indicative of accelerated leukemia development." (PMID 39580581, 2025). "To investigate the role of miR-196b in leukemia initiation by mutant Dnmt3a, we generated Dnmt3a+/–Flt3ITD mice with germline deletion of miR-196b (miR196b–/–Dnmt3a+/–Flt3ITD)." (PMID 39580581, 2025). "Patients with DNMT3A / FLT3ITD mutations, in which leukemia switches from an AP-1 regulatory clone at diagnosis to an mTOR signaling-driven clone at relapse." (PMID 39078434, 2025). "The candidate upstream regulators for some of these genes were TNKS1BP1 (p= 1.78E-05), DNMT3A (p = 5.95E-05) and TET3(p = 2.51E-04), some genes previously associated with leukemia." (PMID 40365343, 2025). "In Npm1−/−/Dnmt3a−/− mice, leukemia is preceded by an extended period of proliferation and self-renewal of myeloid progenitor cells." (PMID 39078434, 2025). "The DNMT3A mutation results in the accumulation of cells in the bone marrow due to impaired differentiation, while ASXL1 is crucial in the pathogenesis of leukemia by altering histone modifications and increasing the risk of transformation to MDS." (PMID 39873798, 2025). "Several studies have focused on DNMT3A gene knockout in human or mouse-sourced cells, including human embryonic stem cells, human leukemia cells K562, mouse hematopoietic stem cells, and mouse somatic cells." (PMID 41450820, 2025).
leukemia (continued). "TET2, ASXL1, DNMT3A, and SF3B1 are all known to harbor causal leukemia variants, and somatic variants in SRSF2 have been described in myelodysplastic syndrome." (PMID 39132489, 2024). "The SMGs identified in our mouse models included well-described melanoma and leukemia oncogenes and tumour suppressors (Muc4, Pten, Grin2a, Dnmt3a, Npm1 and Flt3) reinforcing the WES validation and the subsequent filtering of SMGs." (PMID 39223638, 2024). "Previous mechanistic studies of AZA resistance in human leukemia cell lines found that the mRNA levels of the genes encoding DNMT1, DNMT3a, and DNMT3b were increased in HMA-resistant cells." (PMID 38731939, 2024). "Among the different DNMTs, the DNMT3A has been investigated and reported the most frequently in hematologic malignancies, and its change is presented below in the order of leukemia, lymphoma, and MM, respectively." (PMID 36797244, 2023). "KG-1 cells express wild-type DNA methyltransferase 3 alpha (DNMT3A) and KMT2A and are often used as a control line to study the role of DNMT3A in leukemia development." (PMID 36982453, 2023). "Future prospective studies with large sample size, long-term follow-up, more leukemia cell lines and more mechanism research were recommended to confirm the DNMT3A role in childhood with B-ALL." (PMID 36934225, 2023). "The increased SOCS1 level in the bone marrow of AML patients was closely associated with advanced age, mutations in FLT3-ITD, NPM1, and DNMT3A, and SOCS1 overexpression in zebrafish mimic leukemia phenotype." (PMID 38161382, 2023). "DNA methyltransferase 3A (DNMT3A) catalyzes de novo DNA methylation and plays important roles in the pathogenesis of malignancies including leukemia." (PMID 36934225, 2023). "Despite the epistatic relationship in the DNA methylation-hydroxymethylation pathway, DNMT3A and TET2 mutations are often concurrent in lymphoma and leukemia patients, suggesting that both enzymes sometimes work in parallel to produce a common result." (PMID 36675240, 2023). "The cooperative mechanisms of multiple mutations (e.g., combined DNMT3A, NPM1, and FLT3 mutations) also need to be investigated to better understand the mechanisms of progression to overt leukemia." (PMID 38116120, 2023). "Consistent with their potential roles in CHIP, DNMT3A and TET2 mutations are early events occurring in HSCs during the clonal evolution to leukemia." (PMID 36675240, 2023). "For example, lncRNA MEG3, as a tumor suppressor of AML, its hypermethylation can lead to a decrease in DNMT3A expression, which in turn inhibits the occurrence of leukemia." (PMID 34694569, 2022). "Fibrinogen and collagen in plasma will bind to the surface of GDYO nanosheets, increasing the interaction of GDYO on ITGB2 and MRC2, respectively, and thereby enhancing the anti-leukemia effect of GDYO against DNMT3A-mutant AML cells." (PMID 36163326, 2022). "A closer look into the mutations that persisted following therapy (at remission) in responders revealed that they were in genes associated with pre‐leukaemia (ASXL1, DNMT3A, IDH2, SRSF2 and TET2)." (PMID 36051087, 2022). "Given that Tet2 and Dnmt3a are both epigenetic regulators, we speculate that the increased instability in epigenetic regulation combined with the presence of Flt3ITD/WT mutation likely facilitates the selection of a common set of dysregulated genes, which might contribute to leukemia development." (PMID 36073548, 2022). "DNMT3A, TET2, and ASXL1 (“DTA”) mutations prevalently occur early in pre-leukemia hematopoietic stem and progenitor cells (HSPCs), persist for a long time and are not considered to be associated with poor prognosis." (PMID 35865470, 2022).
leukemia (continued). "Leukemia stem cells (LSCs) have been reported to participate in drug resistance and recurrence of AML24,25, and GDYO significantly decreased the frequency of leukemia progenitor and stem cells in DNMT3A-mutant cells." (PMID 36163326, 2022). "Nevertheless, our work sheds important light on the anti-leukemia efficacy of GDYO against DNMT3A-mutant AML." (PMID 36163326, 2022). "Our novel approach is the assembly of an antibody-based siRNA nanocarrier to induce specific RNAi against mutated DNMT3A and FLT3 in leukemia." (PMID 36457063, 2022). "Here, we demonstrate that cell adhesion-related genes are predominantly enriched in DNMT3A-mutant AML cells and identify that graphdiyne oxide (GDYO) display an anti-leukemia effect specifically against these mutated cells." (PMID 36163326, 2022). "In contrast, all Bcor/Dnmt3A double knockout mice developed AEL-like leukemia characterized by the expansion of Kit+/Ter119+ cells." (PMID 33898929, 2021). "In conclusion, we provide the first demonstration that concurrent Bcor and Dnmt3a loss promotes AEL in mice and sheds light, at least in part, on the cellular and molecular features underlying this leukemia." (PMID 33159179, 2021). "The inhibitory effect of oridonin against DNMT3A R882 mutant leukemia cells can also be observed in vivo." (PMID 34663800, 2021). "In this study, we performed high-throughput screening from FDA-approved drug libraries and natural product libraries to obtain inhibitors targeting DNMT3A R882 mutant leukemia cells." (PMID 34663800, 2021). "In several leukemia mouse models, Dnmt3a has been identified as a tumor suppressor, therefore suggesting a meaningful impact of TCL1A-mediated inhibition of DNMT3A during leukemogenesis." (PMID 34771618, 2021). "Compound 4a, although less potent against DNMT3A in enzyme assay, exhibited high leukemia cells’ growth arrest." (PMID 32075099, 2020). "This NUP98-NSD1-positive PDX model was analyzed in the 6th transplantation and showed AML with normal karyotype, while it was wildtype for genes frequently mutated in leukemia, such as FLT3, NRAS, NPM1, IDH1/2, and DNMT3A." (PMID 32993115, 2020). "Consistently, the regioisomers 2a–c and 4b,c, which were more potent than the prototypes 2 and 4 against DNMT3A, showed antiproliferative effects at submicromolar or single-digit micromolar levels against both the tested leukemia cell lines." (PMID 32075099, 2020). "In genetic modeling such mutations have been shown to de-regulate methylation of both tumor suppressor and differentiation-specific enhancers, and in the case of DNMT3A to control the lineage identity of the resulting leukemia." (PMID 32330454, 2020). "To elucidate the functional role of DNMT3A-WT/MT in KMT2A-PTD-positive leukemia cells, we stably expressed DNMT3A-wild-type (WT), DNMT3A-R882C/H (DNMT3A-MT) and empty vector (EV) control in EOL-1 cells." (PMID 32015320, 2020). "These genes, mostly involved in the leukemia process, were potentially regarded as novel therapeutic targets in AML associated with DNMT3A mutation." (PMID 33299888, 2020). "The relationship between HLH and some subtypes of leukemia such as FLT3-ITD and/or DNMT3A mutations is unclear." (PMID 29843647, 2018). "Deletion of DNMT3a has been shown to promote lung tumour progression and expression has been shown to be higher in leukaemia compared with control cells." (PMID 28251343, 2018). "Several BET inhibitors are in development and have been shown to have activity across various subtypes of AML in mouse models including MLL-fusion leukemias, as well as leukemias bearing mutations in NPM1, Flt3-ITD and DNMT3A." (PMID 29545928, 2018). "For example, upregulation of Dnmt3a promoted AML/ETO-induced leukemia through de novo hypermethylation and a methylation-independent repressor function of Dnmt3a enhanced T-cell lymphomagenesis." (PMID 27563627, 2016).